RN7SL660P (RNA, 7SL, cytoplasmic 660, pseudogene)
Gene: Miscellaneous RNA gene on chromosome 14 (32,442,341 to 32,442,639, forward strand). Ensembl gene ENSG00000278746.
Homologues: Orthologues: chimpanzee Metazoa_SRP (98% identical). Paralogues in human: RN7SL1 (86% identical), RN7SL2 (86% identical), RN7SL3 (84% identical), RN7SL493P (83% identical), RN7SL296P (83% identical), RN7SL326P (82% identical), RN7SL431P (82% identical), RN7SL45P (82% identical), RN7SL478P (82% identical), RN7SL556P (82% identical), RN7SL127P (82% identical), RN7SL444P (82% identical), and 703 more.